CXCR4 (C-X-C motif chemokine receptor 4)
Diseases named in the same sentence as CXCR4 in open-access papers (continued):
Sharing a sentence is not in itself a finding about the gene and the disease.
multiple myeloma (continued). "In 176 paired clinical samples, BTK and CXCR4 expression was lower in myeloma cells purified from a focal lesion than from a random site." (PMID 25083818, 2014). "Although various studies illustrate tumor promoting and prometastatic effects of CXCR4, its expression also plays a pivotal role in haematopoiesis and has recently been reported as a good prognostic indicator in multiple myeloma." (PMID 25474406, 2014). "BTK expression in random-site samples was correlated with proportions of myeloma cells expressing cell surface CXCR4." (PMID 25083818, 2014). "Lymph nodes of patients with B-cell NHL with reduced (0 or 1 AU) expression of CXCR4 gene derived from patients with hairy cell leukemia, multiple myeloma and one patient with mantle cell lymphoma." (PMID 24859274, 2014). "Once these myeloma cells enter the bone marrow, they adhere to the bone marrow stromal cells through the interaction of CXCR4/stromal derived factor (SDF)-1, VLA-4/VCAM-1, LFA-1/ICAM-1, or others." (PMID 24252328, 2013). "On the other hand, hypoxia increases the expression of CXCR4, enhances the homing of circulating myeloma cells to new bone marrow niches, and results in MM dissemination and expansion." (PMID 24252328, 2013). "The precise role of CD138 and CXCR4 in myeloma pathology and management remains to be determined though." (PMID 24376850, 2013). "Seamlessly completing the theranostic loop, the therapeutic counterparts [177Lu]/[90Y]Pentixather deliver targeted radiotherapy to CXCR4-expressing tissues, with pioneering applications in advanced multiple myeloma and acute myeloid leukemia establishing a compelling safety and efficacy profile." (PMID 42244984, 2026). "In our study, we also found that over expressed MMSA-1 could greatly increase VEGF-A level, reduce Ang-1 level and to reduce adhesion molecules expression including E- cadherin, CXCR4 and improve myeloma cells clonogenicity and migration ability, just." (PMID 41535418, 2026). "Interestingly, CXCR4 overexpression in multiple myeloma cells leads to the acquisition of a mesenchymal EMT phenotype, a feature that is frequently associated with stemness." (PMID 38612911, 2024). "In summary, the experimental results indicate that the CXCL12/CXCR4 axis mediates intercellular coupling, indicating that myeloma microhabitats could be used as targets for improving and developing therapeutic approaches." (PMID 37798791, 2023). "For instance, in marginal zone lymphoma (MZL), AML, B-cell chronic lymphocytic leukemia, or multiple myeloma (MM), CXCR4 expression may have prognostic value." (PMID 37290799, 2023). "Taken together, our data demonstrated that CXCL12/CXCR4 axis mediates intercellular coupling thus suggesting that the myeloma niche may be exploited as a target to improve and develop therapeutic approaches." (PMID 35064098, 2022). "Our data further pointed out that CXCR4/CXCL12 pathway may serve as a new strategy to target myeloma niche." (PMID 35064098, 2022). "Furthermore, plerixafor, a selective inhibitor of CXCR4, significantly reduced mitochondrial transfer from MSCs to myeloma PCs further establishing mechanistically that CXCR4/CXCL12 is directly involved in mitochondrial trafficking." (PMID 35064098, 2022). "Indeed, MM patients who failed to respond to BTZ (n = 3) showed higher colocalization of CXCR4 with myeloma PCs compared with patients who responded (n = 3; p < 0.05 versus responders)." (PMID 35064098, 2022). "CXCL12 induced a physical association between CXCR4 and CD45 in multiple myeloma cells." (PMID 35682990, 2022). "The study showed that 14 enabled CXCR4-positive detection in 23 subjects and also detected previously unknown myeloma lesions in 21% of subjects." (PMID 34500609, 2021). "Chronic hypoxia increases the expression of CXCR4 on multiple myelomas in a HIF-1-dependent manner." (PMID 33467722, 2021).
multiple myeloma (continued). "A phase I study will investigate the safety, tolerance and efficacy of CXCR4 modified CAR T cells in patients who failed standard treatment/refractory/relapsed multiple myeloma (NCT04727008) while the CXCR4 antagonist AMD3100 was tested in a variety of tumor types." (PMID 34440844, 2021). "In MCL, as well as other hematological malignancies, such as chronic lymphocytic leukemia and myeloma, CXCR4/CXCL12 is known to mediate tumor cell migration (“homing”) and adhesion to bone marrow stromal cells, which function as a protective microenvironment 6-9." (PMID 33391493, 2021). "F50067, a humanized mAb targeting CXCR4, demonstrated preclinical anti-tumor activity in multiple myeloma, and phase I study was performed to assess the safety and efficacy of F50067 alone and in combination with lenalidomide and dexamethasone in relapsed or refractory multiple myeloma." (PMID 33392074, 2020). "Interestingly, multiple myeloma seems the only malignancy where CXCR4 overexpression improves treatment sensitivity and provides longer median survival time." (PMID 33096815, 2020). "Besides, the previous study demonstrated that Notch signaling controls the expression of SDF-1 and its receptor, CXCR4, and functions in myeloma cell lines and MSCs46." (PMID 32366833, 2020). "Clinical trials with BL-8040 and G-CSF (a glycoprotein that induces stem cell mobilization by decreasing bone marrow SDF-1 and up-regulating CXCR4) have shown a significant increase in CD34+ cell mobilization from the bone marrow for patients that require autologous transplant in myeloma." (PMID 32658899, 2020). "In addition, CXCR4-targeted endoradiotherapy with 177Lu- or 90Y-pentixather were well-tolerated and exerted anti-myeloma activity even at patients with advanced stage multiple myeloma." (PMID 31695804, 2019). "Moreover, CSL can also inhibit the invasion and migration of cultured myeloma cells in vitro and downregulate the expression of CXCR4 and MMP-9 proteins." (PMID 29773987, 2018). "SDF-1 is produced by osteoblast cells and its receptor, CXCR4, is expressed on myeloma cells." (PMID 30108468, 2018). "Moreover, CXCR4 is a new immune-oncological target in the treatment of multiple myeloma, myeloid and solid cancers." (PMID 29721166, 2018). "The interaction between Notch, CXCL12, and CXCR4 might also have a further outcome since high CXCL12 levels in the multiple myeloma niche increase the M2 macrophage population in the immune cell infiltrate." (PMID 30154786, 2018). "In addition, in the multiple myeloma setting a direct positive control of CXCR4 by NOTCH1 has been recently proposed." (PMID 28938632, 2017). "Indeed, it was demonstrated that CXCR4 inhibition was efficacious in AML or multiple myeloma models by enhancing the sensitivity of tumor cells to chemotherapy or other targeted therapy." (PMID 26954567, 2016). "The important roles of CXCR4 in multiple diseases have encouraged the development of clinically viable CXCR4 antagonists, and resulted in the US Food and Drug Administration (FDA) approval of the first CXCR4 antagonist, plerixafor for patients with non-Hodgkin's lymphoma and multiple myeloma." (PMID 25669980, 2015). "Additionally, BKT140, inhibited primary tumor growth and metastasis of head and neck cancer, and showed a CXCR4-dependent preferential cytotoxicity towards malignant cells of hematopoietic origin in multiple myeloma." (PMID 26062132, 2015). "While the role of SDF-1α in the metastatic spread in solid tumors has been clearly established, its role in activation of RhoGTPases has only been described in the context of multiple myeloma where SDF-1α binding to its receptor CXCR4 induces chemotaxis and motility through RhoA activation." (PMID 26231656, 2015). "Because myeloma SP cells up-regulate CXCR4, they may enjoy increased micro-environmental protection relative to bulk myeloma cells." (PMID 26415231, 2015).
multiple myeloma (continued). "We also have demonstrated that MICs over-secrete SDF1 than mature myeloma cells and that treatment of CXCR4 inhibitor, AMD3100, leads to decreased adherence of MICs to MBMSCs, undermined colony formation potential of MICs, and better in vitro and in vivo drug efficacy of Bortezomib(BZM)." (PMID 24475036, 2014). "Interestingly, CXCR4, the chemokine receptor responsible for attracting these cells to these niches is also expressed and functionally active in multiple myeloma cells." (PMID 25272036, 2014). "MOPC315.BM myeloma cells also expressed CXCR4, which is crucial for homing to these niches." (PMID 25272036, 2014). "We and others recently established the biophysical model that myeloma initiating (stem) cells (MICs) trigger the stiffening of their niches via SDF-1/CXCR4 paracrine; The stiffened niches then promote the colonogenesis of MICs and protect them from drug treatment." (PMID 24475036, 2014). "Furthermore, previous studies on human and murine myeloma cells showed that SDF-1 binding to CXCR4 promoted transendothelial migration by upregulating the expression of several integrins, including α4β1." (PMID 23300660, 2012). "Interestingly, trials with a CXCR4-targeted antibody developed by Bristol-Myers Squibb, Ulocuplumab, supported further clinical development for use in Waldenstrom’s macroglobulinemia and multiple myeloma." (PMID 36725964, 2023). "In addition, CXCR4 is not limited to the diagnosis and treatment of multiple myeloma." (PMID 37375261, 2023). "They further demonstrated that standard treatment can reduce differential potential while increase regulon activity, and CXCR4 may represent an attractive therapeutic target, since clinical trials have already tested CXCR4 antagonist for relapsed myeloma and use for other clinical applications." (PMID 37259170, 2023). "Finally, we evaluated whether CXCR4 on myeloma PCs was differently expressed in resistant/refractory MM patients compared to MM ones at diagnosis." (PMID 35064098, 2022). "CXCR4 can also be labelled with the cytotoxic beta-emitters such 177Lu or 90Y generating the novel theranostic agent Pentixather for CXCR4-directed endoradiotherapy [50•], which has already been used, with varying degrees of success, in multiple myeloma and other haemato-oncological diseases." (PMID 35325412, 2022). "Finally, in multiple myeloma (MM) cells, CXCR4 expression correlated with disease progression, chemotherapy resistant MRD, and poor prognosis, while an increase in the CXCL12 serum expression level was associated with increased osteolytic disease and increased BM angiogenesis." (PMID 32260318, 2020). "Indeed, CXCR4 directs the recruitment of monocyte precursors at the tumor site, and M2 macrophages from the BM of myeloma patients express higher levels of CXCR4 compared with patients with the benign form of monoclonal gammopathy of uncertain significance and healthy individuals." (PMID 30154786, 2018). "Consequently, up-regulation of CXCR4 and VLA-4 expression in MM might augment association of myeloma cells to bone cells." (PMID 30108468, 2018). "Therefore, SDF-1α/CXCR4 axis appears to play an important role in myeloma cells-BMSC communication." (PMID 28032590, 2017). "Our data represent the first study on quantitative PET imaging of CXCR4, a key chemokine receptor involved in leukocyte attraction, hematopoietic stem cell homing, tumorigenesis, and many other processes, in preclinical models of myeloma and in a cohort of patients with advanced MM." (PMID 25736399, 2015). "In this study, we demonstrated that after MMSA-1 expression was significantly inhibited, CXCR4 expression was also greatly reduced, which indicating the migration promoting ability of MMSA-1 on myeloma cells." (PMID 41535418, 2026). "Integrating CXCR4-directed ERT into auto- or alloSCT strategies for heavily pretreated lymphoproliferative disorders, including lymphomas and multiple myeloma, has achieved remissions in all evaluated patients 33, 38-40." (PMID 39744224, 2025).
multiple myeloma (continued). "This prevents interaction of CXCR4 with CXCL12 which further reduces α4β1 (VLA-4) and VCAM-1 activation, promoting myeloma cell exit from bone marrow." (PMID 40296907, 2025). "C-X-C motif chemokine receptor 4 (CXCR4) is an alternative molecular target normally expressed on blood cells and highly overexpressed on myeloma cells." (PMID 39207486, 2024). "Another 8 MM patients were then scheduled for CXCR4-directed RLT, and myeloma doses of up to 70 Gy were reported, with CR in 1 patient and PR in 5 subjects (overall survival, 7.5 mo)." (PMID 37290799, 2023). "In multiple myeloma, CXCL12/CXCR4 signaling has been shown to promote proliferation, migration, invasion, metastasis, chemoresistance, and tumor-induced osteoclastogenesis." (PMID 37025604, 2023). "In recent years, different groups have assessed the utility of myeloma-specific agents targeted to myeloma proteins such as CD38 and CXCR4." (PMID 36008121, 2023). "For instance, the therapeutic inhibition of CXCR4 (AMD3100) disrupts the interaction between myeloma cells and the BMSC, re-sensitizing myeloma cells to the PI bortezomib, leading to tumor reduction in vivo." (PMID 36361677, 2022). "Recently, results from a phase Ib/II trial using a fully human IgG4 monoclonal anti-CXCR4 antibody (Ulocuplumab, BMS-936564) were published, showing safe and efficacious clinical use of Ulocuplumab against multiple myeloma." (PMID 35335871, 2022). "TAMs additionally exert direct and indirect effects on neighboring myeloma cells driving the downregulation of important adhesion molecules such as CD138 and CXCR4." (PMID 35847862, 2022). "A study on myeloma found that CXCL12, a key molecule involved in CXCR4-dependent cell retention in bone marrow, was upregulated in circulating plasma cells and potentially induced myeloma cells’ intravasation." (PMID 33802312, 2021). "A humanized monoclonal antibody to CXCR4, ulocuplumab (BMS-936564), has been tested in early phase trials and was well tolerated with some demonstrated clinically efficacy in multiple myeloma patients." (PMID 33805598, 2021). "In contrast, in myeloma cell lines U266 and RPMI8226, chronic hypoxia increases the expression of CXCR4 by increasing the expression of miRNA-210." (PMID 33467722, 2021). "This review summarizes the pleiotropic role of the SDF-1α/CXCR4 axis in multiple myeloma and introduces the SDF-1α/CXCR4 axis-targeted therapies in multiple myeloma." (PMID 33918655, 2021). "Even CXCR4 antagonists had been carried out with AMD3100 (Plerixafor) as a prototypic CXCR4 antagonist which happened to be discovered, and had been approved by the US Food and Drug Administration (USFDA) for the treatment of lymphoma and multiple myeloma." (PMID 33129326, 2020). "We found that FTY720 increased CXCR4 internalization on GAMs, which was similar to the functions of FTY720 used for multiple myeloma treatment." (PMID 32194542, 2020). "The first use of cyclic pentapeptide, 68Ga-Pentixafor for CXCR4 PET imaging and its therapeutic analog 177Lu-Pentixather, in a patient with multiple myeloma showed high tumour-to-kidney and tumour-to-liver uptake ratios of 3.1 and 6.4." (PMID 30823564, 2019). "We here showed that hypoxia-induced miR-210 increased the mRNA expression of VLA-4, CXCR4, IL-6 and TGF-β in myeloma cells." (PMID 30108468, 2018). "We showed a direct correlation between the expression of CXCR4 and VLA4 in myeloma cells with miR-210." (PMID 30108468, 2018). "Similar to our findings here, Bristol-Meyers Squib (BMS) recently discovered a CXCR4-specific monoclonal antibody (BMS-93654) that induces apoptosis in several CXCR4+ tumor models including AML, NHL, and multiple myeloma." (PMID 29682200, 2018). "LY2510924 peptide has been compared in preclinical studies with AMD3100, a CXCR4-targeting small molecule inhibitor that is approved by the United States Food and Drug Administration for HSC mobilization in multiple myeloma and non-Hodgkin’s lymphoma patients." (PMID 29212254, 2017).
multiple myeloma (continued). "Certainly we were able to observe that SDF-1, which binds to CXCR4, and CXCL8 (IL-8) which is a ligand for CXCR1/CXCR2, are also significantly elevated in myeloma." (PMID 28389623, 2017). "Indeed, disruption of the CXCR4–CXCL12 interaction using the CXCR4 antagonist T140 resulted in decreased osteoclast recruitment and lower migration of osteoclast precursors, thus reducing bone resorption in a mouse model of multiple myeloma-mediated focal osteolysis." (PMID 28883822, 2017). "The CXCR4 inhibitor Plerixafor was recently FDA approved for hematopoietic stem cell mobilization in patients with non-hodgkin lymphoma and multiple myelomas." (PMID 26848769, 2016). "The CXCR4 inhibitor AMD3100 is FDA approved for use in patients with non-Hodgkin’s lymphoma and multiple myeloma." (PMID 26920352, 2016). "The CXCR4 inhibitor, AMD3100, interrupts the migration of MM cells to bone marrow stromal cells and sensitizes myeloma cells to overcome drug resistance." (PMID 25897806, 2015). "Notch signaling has been reported to positively control CXCR4/SDF-1 expression and functions in myeloma cell lines, and forced CXCR4 activation partially rescues tumor cells from the effects of Notch inhibition." (PMID 26176534, 2015). "The presence of high levels of CXCR4 and CXCR7 receptors in monocytes led us to study the possible role of the corresponding chemokine ligand, CXCL12, in myeloma-induced monocyte recruitment." (PMID 25526031, 2014). "It has previously been shown that SDF1/CXCR4-induced migration is dependent on activation of downstream BTK in chronic lymphocytic leukaemia (CLL) and multiple myeloma." (PMID 25294819, 2014). "In 2010, the U.S Food and Drug Administration approved the CXCR4 inhibitor plerixafor in patients with non-Hodgkin lymphoma (NHL) and multiple myeloma (MM)." (PMID 24259307, 2013). "Time activity curves of 11C-MET, 18F-FET and 18F-FDG were compared in various human myeloma cell lines and correlated to hallmarks of MM biology, including levels of immunoglobulin (Ig) light chains, proliferation rate, as well as CD138 and CXCR4 expression." (PMID 24376850, 2013). "CXCR4, a homing factor for myeloma cells, was most abundant on OPM-2 cells; in contrast, INA-6 expressed only half as much CXCR4 and MM1.S cells approximately seven times less." (PMID 24376850, 2013). "The first and potent CXCR4 antagonist, Plerixafor, is Food and Drug Administration (FDA) approved for Stem Cell Mobilization in patients with Multiple Myeloma and Non-Hodgkin lymphoma." (PMID 22399057, 2012). "However, many clinical trials have been halted due to severe side effects due to CXCL12 antagonism and the main CXCR4 antagonist used in the clinic is AMD3100 to boost stem cell mobilization in lymphoma and myeloma patients." (PMID 39737176, 2024). "Several CXCR4-antagonist small-molecule compounds have also been investigated, with Plerixafor (AMD3100, Mozobil®) being approved by the US Food and Drug Administration (FDA) in 2008 for multiple myeloma and lymphoma." (PMID 38612911, 2024). "Notch positively controls CXCL12/CXCR4 function in myeloma cell lines, and in vivo blockade of Notch markedly limits myeloma cell infiltration into bone marrow of mouse xenografts." (PMID 35702353, 2022). "AMD3100 was the first CXCR4 inhibitor to receive FDA approval for its utility in bone marrow transplantation procedures and is currently approved by the FDA for the treatment of multiple myeloma and non-Hodgkin’s lymphoma." (PMID 35797269, 2022). "CXCR4 signalling modulators, e.g., plerixafor, an anti-CXCR4 antibody, is being tested in clinical studies in both solid and haematologic cancers (e.g., acute myeloid leukaemia (AML), chronic lymphatic leukaemia (CLL) and multiple myeloma (MM)." (PMID 35008410, 2022).